CD4 (CD4 molecule)
Diseases named in the same sentence as CD4 in open-access papers (continued):
Sharing a sentence is not in itself a finding about the gene and the disease.
colitis (continued). "Intracellular staining of FoxP3 in spleen-derived CD4+ T-cells of mice with T-cell transfer-induced colitis showed enhanced numbers and percentages of FoxP3pos cells, i.e. iTregs, in mice that had received β2i/MECL-1&β5i/LMP7-deficient CD4+ T-cells." (PMID 24740379, 2014). "Accordingly, there was a 4-fold reduction in overall leukocyte numbers in DSS-challenged KO mice relative to Wt animals, with a significantly attenuated accumulation of CD4+ T cells and neutrophils in the colon during experimental colitis." (PMID 24992040, 2014). "In CD4+ T cell- and dextran sodium sulfate-induced models of colitis, Trem1−/− mice displayed significantly attenuated disease that was associated with reduced inflammatory infiltrates and diminished expression of pro-inflammatory cytokines." (PMID 24453980, 2014). "Naïve wt or immunosubunit-deficient CD4+ T-cells were adoptively transferred into RAG1−/− and immunosubunit-deficient RAG1−/− mice and colitis development was determined six weeks later." (PMID 24740379, 2014). "Rag KO recipients of CD8+ T cells from VDR KO mice had more IFN-γ and IL-17A in the SI and colon that corresponded to the increased severity of naïve CD4+ T cell induced colitis." (PMID 24502291, 2014). "We show that naïve CD4+ T-cells of mice that lack the two immunosubunits β2i/MECL-1&β5i/LMP7 cause colitis upon transfer into RAG1−/− mice, which is more severe than colitis induced by transfer of naïve wt CD4+ T-cells." (PMID 24740379, 2014). "We found that 80% of colonic lamina propria CD4+ T cells expressed CXCR6 in the CD45RBhigh T cell-transferred colitis model." (PMID 23840334, 2013). "We here report that CD4+ T cells in the inflamed colon of CD4+CD45RBhigh T cell-transferred colitis model can be divided into two subpopulations according to the expression of CXCR6." (PMID 23840334, 2013). "Cell transfer of wild-type (WT), but not CD69-deficient CD4 T cells, restored the induction of acute colitis in CD69 KO mice, indicating a critical role of CD69 expression in CD4 T cells." (PMID 23785429, 2013). "Earlier, we have showed that increases in CD4+ T cells in the lamina propria of the colon during colitis are mediated in part by CXCL10." (PMID 24278169, 2013). "Treatment with mTORC1-specific inhibitor rapamycin in murine CD4+ T-cell transfer model of colitis also decreases Th17 differentiation and attenuates the decrease in body weights." (PMID 23383714, 2013). "Among the enlarged fraction of α4β7+ CD4+ T cells found during colitis a significant percentage, i.e. about 35% co-expressed P-lig." (PMID 23630623, 2013). "Taken together, these results indicate that antigen-specific CD4+ Foxp3-T cells develop during active colitis, and that they can be found in the spleens of mice after DSS resolution." (PMID 23936123, 2013). "Using two different colitis models we showed that CD69−/− CD4 T cells accumulate preferably in the cLP under the inflammatory conditions." (PMID 23776480, 2013). "Murine experimental colitis models have shown that CD4+ T cells play an important role in the pathogenesis of IBD by producing pro-inflammatory cytokines." (PMID 24116141, 2013). "Experiments with the transfer of WT CD4 T cells into CD69 KO mice restored the induction of colitis." (PMID 23785429, 2013). "By contrast, retransfer of CXCR6− cells evoked colitis similar to that observed in CD4+CD45RBhigh T cell-transferred mice, and resulted in their conversion into CXCR6+ cells." (PMID 23840334, 2013). "As opposed to the in vitro results, the in vivo findings in mice with CD4+ T cell-induced colitis were more consistent with the modeling predictions." (PMID 23592971, 2013). "Deletion of PPARγ in CD4+ T cells impaired mucosal iTreg and enhanced colitogenic Th17 responses in mice with CD4+ T cell-induced colitis." (PMID 23592971, 2013).
colitis (continued). "This study showed CD69 as negative regulator of inflammatory responses in intestine as it decreases the expression of chemotactic receptors and ligands and reduces the accumulation of CD4 T cells in cLP during colitis." (PMID 23776480, 2013). "We have herein demonstrated that both acute and chronic colitis were attenuated in CD69 KO mice, and that the CD69 expressed on CD4 T cells plays an important role in the development of colitis." (PMID 23785429, 2013). "A similar effect of CXCL10 has been noted in potentiating colitis through a massive infiltration of CD4+ T cells, which produce Th1 cytokines." (PMID 24278169, 2013). "In accordance with this observation, the majority of LP CD4+ T cells expressed CXCR6 in the mouse model of colitis induced by adoptive transfer of CD4+CD45RBhigh T cells." (PMID 23840334, 2013). "Interestingly, in the setting of colitis, some CD4+ effector T cells express TCRs normally associated with steady-state Treg cells, suggesting that in the appropriate inflammatory environment, such cells might be skewed toward a highly pathogenic effector phenotype." (PMID 23405904, 2013). "The suppressive activity of LZ-8 was confirmed using a murine model of DSS-induced colitis; the disease was alleviated by the adoptive transfer of LZ-8-treated CD4+ T cells." (PMID 23864893, 2013). "Especially, the importance of lymphopenia-driven proliferation in the development of CD4+ T-cell transfer model of colitis is well documented." (PMID 23383714, 2013). "In conclusion, our data indicate that Nod2 is functional in murine CD4+ T cells but its expression is dispensable for the T cell regulation of colitis." (PMID 24324812, 2013). "BTLA recently has been reported to play a role in promoting the survival of activated T cells in mouse models of graft versus host disease (GVHD), and effector T cells during development of colitis in the CD4+CD45RBhigh T cell transfer model." (PMID 24205057, 2013). "During colitis but also during ileitis, more than 25% of the CD4+ T cells in MLN expressed P-lig which was significantly higher than under homeostatic conditions." (PMID 23630623, 2013). "Essentially all P-lig+ CD4+ cells within MLN of colitis mice co-expressed the 130 kDa isoform of CD43 indicating C2GlcNAcT-I activity in these cells." (PMID 23630623, 2013). "In DSS colitis CD69−/− CD4 T cell accumulation in colonic lamina propria (cLP) was associated with increased expression of CCL-1, CXCL-10 and CCL-19 genes." (PMID 23776480, 2013). "AT colitis model consists in syngeneic transfer of naïve CD4+ T cells into lymphopenic mice, thus CD8+ T cells and regulatory T cells are normally absent or very limited in numbers (due to poor contamination of inoculums)." (PMID 23725086, 2013). "The CD4+CD45RBhigh cell-induced colitis is mainly mediated by a Th1-dominant inflammatory response and contribution of the Th17-response in this model is relatively minor." (PMID 23840334, 2013). "This demonstrates that potentially pro-inflammatory, antigen-specific CD4+ T cells do develop during DSS colitis and that they can be tracked, making the DSS model more useful for T cell research." (PMID 23936123, 2013). "Since 1993, a role for a CD4 subset (CD45 RBlo) in the prevention of the colitis induced in immunodeficient mice by the transfer of naïve T cells has been demonstrated." (PMID 24063002, 2013). "Most CD4+ T cells in colonic LP strongly expressed CXCR6 in colitis model mice at 8 weeks after adoptive transfer." (PMID 23840334, 2013). "We have shown here that LZ-8-induced CD4+ T cells alleviates colitis, and it has previously been shown that LZ-8 possesses immunosuppressive activity and can prevent insulitis in nonobese diabetic mice and prolong allograft survival." (PMID 23864893, 2013). "During colitis, CD4+ TCM cells increased significantly in both the colons (P < 0.001) and the mLNs (P < 0.0001)." (PMID 23936123, 2013).
colitis (continued). "Nonetheless, although we have demonstrated the potential of LZ-8-induced CD4+ T cell on ameliorating mice colitis, further experiments are required to define the effect and action mechanism of LZ-8 as an immuno therapeutic agent." (PMID 23864893, 2013). "Development of colitis in IL-10−/− appears to be mediated by CD4+ T cells and an uncontrolled Th1 response." (PMID 22400037, 2012). "The suppression of DSS-induced colitis by bortezomib treatment correlated with a decrease in CD4+ and CD8+ T cell accumulation both in the colon and mesenteric lymph nodes." (PMID 22479648, 2012). "Recently, Mikami and coworkers showed that cotransfer of the mixed Th1/Th17 CD4+ T cells from IL-10−/− with colitis with Th1 CD4+ T cells from CD4+CD45high-induced RAG−/− mice with colitis into RAG−/− mice ameliorate wasting disease." (PMID 22400037, 2012). "The Gαi2−/− mice were first grouped according to their macroscopic colitis scores and the fraction and number of the different thymocyte populations (DP, CD4 SP and CD8 SP) was analyzed." (PMID 22590596, 2012). "In this study, bortezomib administration substantially reduced the severity of DSS-induced colitis as well as significantly enhancing apoptosis and IκB expression of CD4+ and CD8+ T cells during DSS-induced colitis." (PMID 22479648, 2012). "Mouse models of intestinal inflammation have also pinpointed a key role for Treg cells in intestinal homeostasis, as illustrated in a model of T cell–driven colitis induced by the transfer of naive CD4+ T cells into RAG−/− mice." (PMID 22849659, 2012). "Our next step was to analyze the frequency of CD4+LAP+ T cells during colitis development in these mice." (PMID 22400037, 2012). "The influence of Foxp3+ Treg on intestinal inflammation was tested using the CD4+ T-cell transfer colitis model in Rag−/− C57BL/6 mice and the acute DSS-colitis model." (PMID 22849659, 2012). "A more equivalent study using a murine colitis model showed a control of CD4+ T cells by NK cells in vivo." (PMID 23077546, 2012). "Despite the absent intestinal inflammation in young mice, we found enhanced frequency of CD4+ T cells expressing a memory phenotype (CD44high) in the large intestinal mucosa before the establishment of colitis (6 weeks of age)." (PMID 22400037, 2012). "In another mouse model of colitis, oral ingestion of Lactobacillus casei alleviated colitis and increased the suppressive function of CD4+Foxp3+ Tregs." (PMID 22970150, 2012). "The frequency of CD4 and CD8 SP thymocytes increased gradually and significantly with the progression of colitis in Gαi2−/− mice, compared to ∼16% of CD4 SP and ∼8% of CD8 SP thymocytes in the control mice." (PMID 22590596, 2012). "The use of a toxin-conjugated anti-IL-7Rα antibody (A7R34) by Yamazaki and colleagues suggests that selective elimination of IL-7Rαhigh CD4+ LPL is required to treat colitis." (PMID 23057802, 2012). "Our studies using Mdr1a−/− and Rag2−/− mice strongly suggest that cells other than CD4+ T cells are important in bacterial-induced colitis." (PMID 23057802, 2012). "CD4+Foxp3+ Tregs were able to control Th17 and Th17+Th1 cells in an IL-10-dependent manner in mice colitis." (PMID 22032685, 2011). "Daily administration of W-061 resulted in improvement of DSS-induced colitis, and significantly reduced the number of CD4+ T cells in the colonic lamina propria." (PMID 21931623, 2011). "Activation of CD4+ CD69+ T cells was more related to the presence of colitis, whereas activated B lymphocytes (CD 19+ CD21+) were more frequent in the obese groups." (PMID 22073943, 2011). "Prevention of the CD45RBhigh CD4+ T cell transfer colitis model in immuno-compromised animals can be achieved by cotransferring Regulatory T cells (Tregs)." (PMID 21283540, 2011). "We found a significant increase in the percentage of splenic, MLN and LP CD4+T cells that expressed CXCR3+ during DSS induced colitis, which was reversed following TCDD treatment." (PMID 21858153, 2011).
colitis (continued). "Even in young mice, before the age of onset of frank colitis, Gái2−/− CD4+ T cells are pushed towards this phenotype." (PMID 21966415, 2011). "FTY720 was also reported to be effective for the treatment of colitis in IL-10-deficient mice, DSS-induced colitis and CD4+CD62L+ cell-transfer model." (PMID 21931623, 2011). "The naturally arising CD4+ CD25+ Tregs have been shown to prevent or even cure colitis in the T cell transfer model." (PMID 21858153, 2011). "In a CD4+ CD45RBhigh cell-transfer colitis model, the development of colitis was suppressed by concomitant transfer of CD4+ CD25+ T cells." (PMID 21931623, 2011). "To directly investigate the role of HVEM-mediated signaling to CD4+ T cells we used an experimental model whereby colitis is initiated by the transfer of CD4+CD45RBhigh T cells into immuno-deficient hosts." (PMID 21533159, 2011). "Although the role of Th1 is reported to be an indispensable subset, the role of Th17 remains controversial in DSS-induced colitis or the CD4+ CD45RBhigh lymphocyte transfer model." (PMID 21931623, 2011). "Two models of IBD were employed: i) chemical-induced colitis primarily mediated by innate immune cells; and ii) colitis initiated by CD4+CD45RBhigh T cells following their transfer into immuno-deficient RAG1-/- hosts." (PMID 21533159, 2011). "Similar suppression of colitis was observed when both naYve CD4+CD45RBhi T cells and CD4+CD25+ Treg isolated from B6.TLR2–/– mice were co-transferred into B6.RAG–/– recipients." (PMID 19950179, 2010). "According to recent results it seems likely that increased secretion of IL-10 participates in protection from colitis after transfer of CD4+ T cells from CpG-ODN-treated donors." (PMID 21188217, 2010). "CD4cre mice have significantly fewer CD4+FoxP3+ Tregs in blood and IL10-expressing CD4+ T cells in the MLN on day 7 of DSS colitis in comparison to WT mice." (PMID 20537136, 2010). "For a control, we also transferred a 1:1 ratio of CD45.2− and CD45.2+ WT naive CD4+ T cells and allowed mice to develop wasting disease and colitis." (PMID 20732640, 2010). "To further investigate this, we used the T cell transfer model of colitis, where transfer of CD4+CD45RBhi T cells to immunodeficient hosts leads to mucosal and systemic inflammation." (PMID 20399121, 2010). "Regulatory T cell (Treg) PPARγ is involved in maintaining homeostasis at the gastrointestinal tract and preventing chronic CD4+ T cell-induced colitis." (PMID 20537136, 2010). "Histological score of mice in CD4+CD62L+ transfer model of colitis was higher compared to control mice." (PMID 19787068, 2009). "It has been reported that CXCL10 triggers lymphocyte adhesion to immobilized integrin ligands and enhances colitis through a massive infiltration of CD4+ T cells, which produce Th1 cytokines." (PMID 18957084, 2008). "In accordance with this view, CD4+CD25+ Treg cells are able to suppress innate immune cells in a model of bacteria-induced colitis." (PMID 15743476, 2005). "We investigated whether TRIP13 exerts anti-inflammatory effect through Treg expansion in a mouse colitis model induced by transferring naïve CD4+ T cells into lymphopenic Rag1−/− mice (CD45.2+)." (PMID 41535263, 2026). "Furthermore, the transfer of intestinal CD4+TRM cells into RAG2−/− mice also induces experimental colitis." (PMID 40529369, 2025). "Using CD4CRE CREBfl/fl mice, they showed that these cells prevented colitis in a Rag2-/- model; however, their model had the disadvantage that the CD4 cells of these mice expressed lower amounts of IL-2, which could have hampered iTreg induction." (PMID 40777015, 2025). "Additionally, Bhlhe40-deficient CD4+ T cells fail to induce colitis in a T cell transfer colitis model, further supporting our finding that induction of BHLHE40 expression in pathologically relevant CD4+ T cells in the gut is pathogenic to colitis." (PMID 40906156, 2025).
colitis (continued). "We hypothesize that, in particular, the enhanced IL-10 secretion prevented colitis in Rag-/- mice that received Foxp3creCREBfl/fl CD4+ T cells." (PMID 40777015, 2025). "Moreover, CD4+Notch2+Foxp3lo T cells are present in the laminar propria of mice with experimental colitis and in that of humans with UC, whose population is phenotypically similar to that observed in an EAE mouse model." (PMID 40702356, 2025). "For functional relevance, a CD4 T cell mediated transfer colitis was performed." (PMID 40777015, 2025). "However, sulfasalazine treatment led to an increase in these cell populations, with a significant rise in CD4+ T cells, indicating a potential immunoregulatory effect that promotes recovery during colitis." (PMID 40977735, 2025). "Importantly, studies have highlighted that effector T cells, in particular CD4+ T cells, can release endogenous opioid peptides called enkephalins, that are able to alleviate pain in different inflammatory contexts, including colitis." (PMID 40300021, 2025). "Additionally, PGE2 signaling suppresses CD4+ T-cell activation in the lamina propria and the development of colitis in a mouse model of dextran sodium sulfate-induced colitis." (PMID 40136444, 2025). "Moreover, our unpublished findings indicate that IOP influences the differentiation of CD4+ T cells, reducing the pro-inflammatory Th1 cells and promoting the anti-inflammatory Treg cells, ultimately improving colitis symptoms." (PMID 40732305, 2025). "Besides, ATG7 was upregulated in CD4+ T cells at inflammatory loci in patients with colitis from single cell sequencing database (GSE226875)." (PMID 40887825, 2025). "Interestingly, during acute colitis, colonic CD4+ and CD8+ T cells showed higher glucose consumption, which went back to baseline levels during the remission phase." (PMID 41007657, 2025). "However, the exact role of Atg7 expressed in CD4+ T cells in maintaining gut homeostasis during colitis continues to be explored." (PMID 40887825, 2025). "Our results show that during chronic DSS-induced colitis, colon CD4+ and CD8+ T cells produce fewer mitochondrial reactive oxygen species (mROS) and have reduced-mitochondria sizes; this phenotype is only transient and normalizes during the remission phase of the disease." (PMID 41007657, 2025). "Given that IL-18 is found in elevated levels in UC patients, a study that used wild type (WT), IL-18-/-, and IL-18R-/- mice in DSS colitis model found that IFNγ production and IL-17 producing CD4+ T cells were reduced in the colons of both knockout models, along with less severe colitis than WT." (PMID 40642091, 2025). "To evaluate the therapeutic efficacy of dual-targeting EVs in vivo, we established a humanized colitis mouse model in which NSG mice were adoptively transferred with human PBMCs or CD4+ T cells, followed by induction of colitis using trinitrobenzene sulfonic acid (TNBS)." (PMID 41444211, 2025). "Transfer of CD4+ CD45RBlow cells protected from CD4+ CD45RBhigh cell-mediated colitis." (PMID 40649879, 2025). "Importantly, CD4+ T cells overexpressing Bcl‐3 fail to induce colitis in a T cell transfer‐induced colitis experiment, presumably due to impaired proliferation of these cells in vivo, which is a prerequisite for inducing colitis in this model." (PMID 40359334, 2025). "Mechanistically, isobutyrate can increase the relative abundance of Lactobacillus reuteri, thereby increasing the production of indole-3-lactic acid, regulating aryl hydrocarbon receptor expression and downstream signaling pathways, and regulating Foxp3+ CD4+ T cell recruitment to alleviate colitis." (PMID 40342298, 2025).